NQO1 (NAD(P)H quinone dehydrogenase 1)
Diseases named in the same sentence as NQO1 in open-access papers (continued):
Sharing a sentence is not in itself a finding about the gene and the disease.
diabetes (39 papers, 2008 to 2025). "Nrf2 signaling has been reported to be implicated in preventing the onset of diabetes, and HO-1 and NQO1 are phase II antioxidant enzymes that are regulated by Nrf2 signaling." (PMID 38040681, 2023). "In the present study, we aimed to investigate the protective effects and underlying mechanisms of NQO1 on diabetes-induced renal tubular epithelial cell oxidative stress and apoptosis." (PMID 35090502, 2022). "At present, diabetes caused a significant down-regulation of Nrf2 and downstream molecules such as NQO-1 and Prdx-1, and CVB-D alleviated the expression of these proteins both in vivo and in vitro." (PMID 32286474, 2020). "Polymorphisms in HMOX1 and NQO1 have been associated with several oxidative stress-related diseases, including cancer, diabetes, and Alzheimer’s disease." (PMID 25933176, 2015). "Recent research revealed that melatonin reduced kidney damage caused by diabetes and exerted neuroprotective effects by activating the Nrf2/heme oxygenase-1 (HO-1) pathway and increasing levels of the antioxidant enzymes HO-1 and NAD(P)H dehydrogenase [quinone] 1 (NQO1)." (PMID 33343809, 2020). "In addition, the decreased sciatic nerve protein levels of Nrf2 and NQO1 associated to diabetes were reversed by SFN treatment, which also enhanced the expression of HO-1 and reduced the phosphorylation of JNK in the sciatic nerve of diabetic mice." (PMID 28700700, 2017). "Oral administration of EeSs boosted the expression of Sod1, Cat, Gpx-1, Hmox-1, and Nqo-1 mRNA levels in the diabetic mice liver, suggesting that EeSs has a strong antioxidant potential to quince free radicals and hence the ability to prevent diabetes-associated complication." (PMID 28607575, 2017). "In the diabetes model group, the mRNA expression levels of Nrf2, HO-1, NQO1, and γ-GCS showed a significant decrease when compared to those in the normal group (p < 0.05)." (PMID 38560269, 2024). "We also found decreased Nrf2 signaling and the expression of the enzyme NQO1 under diabetes circumstances, further corroborating the earlier findings." (PMID 39062016, 2024). "In our study, HNCP treatment significantly increased the n-Nrf2 expression and downstream proteins HO-1 and NQO1 in STZ-induced diabetes mice." (PMID 37888453, 2023). "It is well established that HO-1 and NQO1 play a key protective role against oxidative stress, including in diabetes and the prevention of diabetic complications." (PMID 37834034, 2023). "In our current study, we found that NQO1 was reduced in the kidneys of patients with type 2 diabetes mellitus with nephropathy and db/db mice, especially in renal tubules." (PMID 35090502, 2022). "NQO1 overexpression notably inhibited diabetes-induced Cleaved Caspase-3 expression and reversed the ratio of Bax to Bcl-2 in kidneys." (PMID 35090502, 2022). "The NAD(P)H quinone dehydrogenase-1 (NQO-1; EC 1.6.5.2) is a downstream target of Nrf2 in protection against diabetes and metabolic disorders." (PMID 34946740, 2021). "NRF2 activates the transcription of a cohort of antioxidant genes, such as heme oxygenase-1 (Ho1) and NAD(P)H dehydrogenase quinone 1 (Nqo1), the proteins of which work as scavengers of diabetes-induced free radicals." (PMID 28698767, 2017). "Collectively, our findings suggested that YNJ could effectively ameliorate cardiomyopathy induced by diabetes possibly through SIRT1/Nrf2/NQO1 signaling." (PMID 37288289, 2023). "The relation between the presence of diabetes and Nrf2 protein concentrations was analyzed since a significantly higher plasma concentration of the Nrf2 target NQO1 had been reported in plasma from diabetic patients, pointing to higher Nrf2 activity in diabetes." (PMID 37107307, 2023). "Therefore, to further elucidate the function of NQO1 in renal tubular cells in diabetes mellitus, we overexpressed NQO1 in HK-2 cells treated with HG using the pcDNA3.1(+) plasmid targeting NQO1." (PMID 35090502, 2022).
diabetes (continued). "Furthermore, it was revealed that SPP significantly abrogated oxidative stress not only by activating the Nrf2 gene but also by activating two Nrf2-targeted antioxidative genes (NQO-1 and HO-1) compared with metformin hydrochloride, which is widely accepted as a diabetes drug." (PMID 35518685, 2019). "Indeed, NQO1 knockout diabetic mice had increased hyperglycemia and higher ROS expression, revealing the important neuroprotective role played by this enzyme during diabetes." (PMID 28700700, 2017). "In the present study, we observe that in diabetes, expression of NAD(P)Hdehydrogenase 1 (Nqo1) and glutathione S-transferase P (Gstp1) is significantlydownregulated in RMVs while it is not changed in BMVs." (PMID 36606460, 2023). "Of the top 15 proteins found by Cytoscape 3.6.1, 8, CAT and OGG1 (downregulated) and CASP3, COMT, CYP1B1, DPYD, NQO1, and PTGS1 (upregulated), were dysregulated in diabetes-related kidney disease." (PMID 34367469, 2021). "Consistent with Nrf2 protein levels, in wild-type mice, both diabetes and MG132 increased NQO-1 mRNA levels." (PMID 28373900, 2017). "Diabetes also slightly up-regulated the expression of p-Nrf2 protein and the expression of Nrf2-downstream antioxidant genes: CAT and NQO-1." (PMID 24720784, 2014). "The expression of the transcription factor NF-E2-related factor 2 (Nrf2) in the nucleus and its target genes heme oxygenase-1 (HO-1) and NAD(P)H:quinone oxidoreductase 1 (NQO1) at the 20th and 24th weeks of diabetes was significantly increased in the db/db mice compared with the db/m mice." (PMID 32194828, 2020). "It should be noted that in the present study, diabetes also increased aortic Nrf2 expression and its downstream CAT and NQO-1 gene expression, which suggests that Nrf2 acts as a protective mechanism at certain early stages to be up-regulated with the attempt to protecting the tissue." (PMID 24720784, 2014). "Diabetic kidneys had increased transcript and membrane-bound protein levels of Nox4, the renal-specific generator of cytosolic reactive oxygen species (ROS) and reduced expression of SOD2, UCP2, GPX3, NQO1, and CAT." (PMID 23149823, 2013). "Gene expression of NQO1 was significantly reduced in non-diabetic and diabetic BPH mice as compared to BPN mice, whilst expression of Nrf2 and HO-1 were unaffected by either hypertension or diabetes." (PMID 37253814, 2023).
prostate carcinoma (34 papers, 2004 to 2025). A carcinoma that arises from epithelial cells of the prostate gland. "Consistent with the expression of low NQO1 and tumor metastasis in multiple cohorts, a strong association was observed between NQO1 mRNA expression and prognosis of prostate cancer patients." (PMID 31909204, 2020). "NQO1 message and protein is reduced in advanced prostate cancer, is associated with survival in multiple cohorts and biochemical recurrence (BCR) in circulating tumor cells (CTC) obtained from prostate cancer patients." (PMID 31909204, 2020). "Biopsy specimens and circulating tumor cells showed biochemical recurrent prostate cancer was associated with low NQO1." (PMID 31909204, 2020). "We therefore analyzed the distribution of the NQO1 P187S SNP (single nucleotide polymorphism) in prostate cancer patients and a healthy control group." (PMID 23109831, 2012). "Additionally, the Cur treatment changed the methylation status of the NRF2 gene’s CpG promoter region, causing NRF2 and its target gene, NQO-1, to be expressed again and thus having a chemopreventive impact on prostate cancer." (PMID 39125934, 2024). "NQO1 knockdown inhibits ROS generation in prostate cancer cells; therefore, NQO1 upregulation may be associated with ROS induction." (PMID 34209212, 2021). "In the future, experimental models can be used to determine if NQO1 is causal for prostate cancer cells to home to different metastatic sites given our observations of heterogeneity in downstream signaling and functional output in prostate cancer cells isolated from different metastatic sites." (PMID 31909204, 2020). "The NQO1 gene polymorphism with the TT genotype was found in 12.7% of the patients with esophageal, 16.8% with stomach, 13.5% with colorectal, 9.7% with rectal, 17.7% with lung, 14.3% with breast, and 16.1% with prostate cancers and in 15.7% of patients with lymphoma." (PMID 34356648, 2021). "Another study reported that BA had an antioxidant effect due to increased Nrf2 and Nqo1 mRNA expressions in mouse embryonic fibroblast and human prostate cancer cells." (PMID 38700634, 2025). "Genes associated with ETV4-fusion-positive prostate cancers were used as the input, and four therapeutic candidate targets, PARP1, NQO1, HSPA5, and TOP1, and the respective selective drugs, olaparib, amrubicin, fluorouracil, and irinotecan, were identified." (PMID 36289913, 2022). "In support of this view, inhibition of NQO1 in PC3 prostate cancer cells reduced the cytotoxic effects of IQ." (PMID 34209047, 2021). "NQO1 expression decreased consistently in metastatic prostate cancer samples in multiple independent studies." (PMID 31909204, 2020). "TGFβ treatment of prostate cancer cells decreased NQO1 levels and mimicked molecular changes of NQO1 knockdown cells." (PMID 31909204, 2020). "The proposed model, provides an explanation for how NQO1 overcomes the vulnerability to cellular stress, to obstruct prostate cancer cell plasticity that is essential for its progression to aggressive disease." (PMID 31909204, 2020). "Taken together, these results show that NQO1 inhibition plays a critical role in the repression of E-cadherin and enhancing the motility of prostate cancer cells." (PMID 31909204, 2020). "Together our results provide evidence that NQO1 acts as a guardian to protect prostate cancer cells from undergoing TGFβ-mediated EMT changes that are associated with advanced disease progression." (PMID 31909204, 2020). "Previously we showed that knockdown of NQO1 (NQO1low) prostate cancer cells upregulate pro-inflammatory cytokines and survival under hormone-deprived conditions." (PMID 31909204, 2020). "We had reported that NQO1 attenuation fueled pro-inflammatory signaling and promoted androgen-independent prostate cancer cell survival." (PMID 31909204, 2020).
prostate carcinoma (continued). "Collectively, this work reveals a possible new gatekeeper role for NQO1 in counteracting cellular plasticity in prostate cancer cells." (PMID 31909204, 2020). "Recently, hyperactivation of poly (ADP-ribose) polymerase-1 (PARP-1) has been suggested to play an important role in β-lap-induced radiosensitization in prostate cancer cells that overexpress NQO1." (PMID 21998736, 2011). "We have shown previously that sulforaphane, curcumin, dimethyl fumarate and, to a lesser degree, β-naphthoflavone will induce modest increases NQO1 enzymatic activity in prostate cancer cells in vitro." (PMID 16539699, 2006). "We also have demonstrated that sulforaphane, an isothiocyanate found in cruciferous vegetables, induces NQO1, glutathione synthetic enzymes and glutathione transferases in several human prostate cancer cells." (PMID 16539699, 2006). "The objective of the current studies was to examine the role of caspase 3 (CPP32) and NAD(P)H:quinone oxidoreductase (NQO1) in the signaling of genistein-and β-lapachone (bLap)-induced apoptosis in human prostate carcinoma cells PC3." (PMID 15315711, 2004). "The observation that MMTSO caused downregulation of GCLC, GSR, and NQO1 genes provides evidence that MMTSO could play a role in oxidative stress and antioxidant defense of prostate cancer." (PMID 40059483, 2025). "Meanwhile, in the less reactive DU145 prostate carcinoma cell line, NQO1 was found upregulated." (PMID 37415761, 2023). "Genistein in combination with β-lapachone, a quinone from Tabebuia avellanedae having 3,4-dihydro-2H-benzo [h]chromene-5,6-dione structure induced apoptosis in prostate cancer through synergistic activation of caspase 3 and NAD(P)H:quinone oxidoreductase (NQO1) dependent pathways respectively." (PMID 35422844, 2022). "Therefore, we assessed the role of NQO1 in prostate cancer metastasis using prostate cancer cell culture models (PC-3 NQO1 knockdown and ARCaP EMT model systems)." (PMID 31909204, 2020). "However, it is fascinating to note that NQO1 expression levels are significantly low in metastatic tissues derived from multiple sites of prostate cancer patients suggesting a possible gatekeeper role against metastasis." (PMID 31909204, 2020). "To determine whether NQO1 predicts prostate cancer patient outcomes, we investigated the correlation and prognostic implication of NQO1 in two independent cohorts GSE70769 and GSE40272 using PROGgeneV231." (PMID 31909204, 2020). "Additional work is needed to determine if NQO1 plays a role in the ability of cancer cells to home to different metastatic sites given our observations of heterogeneity in downstream signaling and functional output in prostate cancer cells." (PMID 31909204, 2020). "Another study indicated that the induction of androgen-independent prostate cancer cell apoptosis by puerarin is associated with the suppression of the Keap1/Nrf2/ARE signaling pathway, and puerarin pretreatment resulted in an increase in Keap1 and decline in Nrf2, HO-1, and NQO1 protein expression." (PMID 35935578, 2022). "Moreover, NQO1 knockdown suppressed oxidative stress in prostate cancer cells." (PMID 34573042, 2021). "PARP1, NQO1, HSPA5, and TOP1 were identified as potential molecular targets for ETV4-fusion-positive prostate cancer, and olaparib, amrubicin, fluorouracil, and irinotecan were suggested as candidate drugs, respectively." (PMID 36289913, 2022). "In summary, we show that NQO1 regulates TGFβ signaling to inhibit EMT and migration, which are required for prostate cancer progression." (PMID 31909204, 2020). "Notably, the pattern of NQO1 induction across compounds differed between prostate cancer cell lines and a human liver cell line, suggesting that there could be significant differences in the response of prostate cells to phase 2 enzyme inducing agents compared to other tissue types." (PMID 16539699, 2006).
prostate carcinoma (continued). "Although we did not screen many markers of EMT changes, there was no consistent change in classic EMT markers in other prostate cancer cell lines with NQO1 knockdown." (PMID 31909204, 2020). "Our results suggest that including NQO1 as a marker of disease progression (e.g., BCR) in molecular analyses and combining this with histopathological profiles could help stratify patients for aggressiveness of prostate cancer." (PMID 31909204, 2020). "Recent reports have suggested that by β-lapachone-induced apoptosis is non-caspase mediated in breast and prostate cancer cells, and that the cytotocxicity of this compound is dependent on the activity of NAD(P)H:Quinone oxidoreductase enzyme (NQO1/xip3)." (PMID 15315711, 2004).
melanoma (32 papers, 1999 to 2025). A malignant, usually aggressive tumor composed of atypical, neoplastic melanocytes. "When melanoma cells experience UBIAD1/CoQ10/NQO1 loss, ROS levels increase and promote lipid peroxidation as well as apoptotic cell death." (PMID 35255427, 2022). "An antagonistic regulation between cofactor-free apo NQO1 and reduced 20S proteasome activity had been shown to cause protein aggregation in murine melanoma cells starved of riboflavin." (PMID 34311585, 2021). "Using label-free quantitative mass spectrometry, we identified proteins associated with wild-type NQO1 in melanoma cells under normal or riboflavin-deficient conditions." (PMID 32895367, 2020). "Pretreatment with the NQO1 inhibitor increased the IC50 of 17-AAG by more than 2-fold in all melanoma cell lines tested and in NSCLC cell lines with KEAP1 mutation." (PMID 27045471, 2016). "It is possible that NQO1 is directly or indirectly associated with MITF activity in melanomas and, therefore, might be involved with a proliferative phenotype over an invasive one." (PMID 35326683, 2022). "A previous report showed that, in melanoma, NQO1 mediates activation of the NF-κB component p50 through stabilization of BCL3-induced cell cycle progression and proliferation." (PMID 36793872, 2023). "Conversely, in melanoma and non-small cell lung cancer cell lines, the NQO1 expression levels were negatively correlated with sensitivity to 17-AAG." (PMID 37583897, 2023). "•NQO1 is required for UBIAD1/CoQ10-mediated melanoma lipid peroxidation protection and cell survival." (PMID 35255427, 2022). "As with many other NRF2 antioxidant transcriptional targets, NQO1 has been shown to be upregulated in melanomas and other cancers." (PMID 35326683, 2022). "This view is supported by our findings that UBIAD1/CoQ10/NQO1 axis disruption is sufficient to trigger cell death in melanoma cell lines despite the presence of other antioxidant enzymes." (PMID 35255427, 2022). "For this purpose, we evaluated FSP1 and NQO1 protein and mRNA levels in a panel of melanoma cell lines." (PMID 35255427, 2022). "To study the function of NQO1 in melanoma cells, we examined ROS and lipid peroxidation levels in SKMel28, A375 and Mel Juso cell after NQO1KD." (PMID 35255427, 2022). "For this purpose, we carefully titered UBIAD1 and NQO1 knockdown in SkMel28 and A375 melanoma cell lines at suboptimal level (UBIAD1KD Low and NQO1KD Low) to avoid complete cell death as for UBIAD1KD and NQO1KD." (PMID 35255427, 2022). "The effect of UBIAD1/CoQ10 and NQO1 in survival of melanoma cell lines in vitro suggests to further consider these two enzymes as new therapeutic targets in melanoma research." (PMID 35255427, 2022). "In this study, we showed that UBIAD1, a transmembrane enzyme localized in the Golgi apparatus, plays a key role in suppressing lipid peroxidation and promoting melanoma survival through CoQ10 synthesis and NQO1-dependent plasma membrane redox regulation." (PMID 35255427, 2022). "It has been shown that NQO1 plays a key role in melanomagenesis and is highly expressed in melanoma." (PMID 35255427, 2022). "To further explore the role of NQO1 in melanoma cells-survival, we knock-downed NQO1 in SkMel28 and A375 melanoma cells and performed cell proliferation assays." (PMID 35255427, 2022). "In melanoma cell lines, NQO1 has been demonstrated to promote proliferation by promoting cell-cycle progression." (PMID 35326683, 2022). "In summary, we suggest that NQO1 protein is responsible for CoQ10 redox regeneration downstream of the UBIAD1/CoQ10 axis in melanoma cell lines." (PMID 35255427, 2022). "This evidence further indicates that NQO1 enzyme counteracts lipid peroxidation and ROS generation in melanoma cells." (PMID 35255427, 2022). "We conclude that NQO1 is located downstream of UBIAD1 and cooperates with it to protect BRAF-mutated melanoma cells from lipid peroxidation and cell death." (PMID 35255427, 2022).